TGIF2LY (TGFB induced factor homeobox 2 like Y-linked)
Description:
May have a transcription role in testis. May act as a competitor/regulator of TGIF2LX.
Synonyms: TGIFLY
Tractability: No criterion of Open Targets' tractability assessment is met for any kind of drug.
Gene: Protein-coding gene on chromosome Y (3,579,067 to 3,580,041, forward strand). Ensembl gene ENSG00000176679.
Subcellular location: Nucleus
Gene Ontology:
Molecular function: protein binding; sequence-specific double-stranded DNA binding; DNA-binding transcription factor activity, RNA polymerase II-specific; DNA-binding transcription repressor activity, RNA polymerase II-specific; RNA polymerase II cis-regulatory region sequence-specific DNA binding; DNA binding
Biological process: negative regulation of transcription by RNA polymerase II; regulation of DNA-templated transcription
Cellular component: chromatin; nucleus
Homologues: Orthologues: dog TGIF2LX (48% identical), rat Tgif2lx2 (34% identical), Drosophila melanogaster achi (30% identical), Drosophila melanogaster vis (29% identical), mouse Tgif2lx1 (29% identical), mouse Tgif2lx2 (29% identical), Drosophila melanogaster hth (19% identical), Caenorhabditis elegans ceh-60 (18% identical), Caenorhabditis elegans unc-62 (17% identical), Drosophila melanogaster exd (15% identical), Caenorhabditis elegans ceh-20 (14% identical), zebrafish pbx4 (14% identical), and 1 more. Paralogues in human: TGIF2LX (84% identical), TGIF2 (33% identical), TGIF1 (30% identical), PKNOX2 (23% identical), MEIS2 (21% identical), MEIS3P2 (21% identical), MEIS3 (20% identical), MEIS1 (19% identical), PKNOX1 (19% identical), PBX3 (17% identical), PBX1 (16% identical), PBX2 (16% identical), and 1 more.
Diseases named in the same sentence as TGIF2LY in open-access papers:
TGIF2LY is named in the same sentence as 1 disease in open-access papers, as found by Europe PMC text mining. Sharing a sentence is not in itself a finding about the gene and the disease.
TGIF2LY shares sentences with these, for which no sentence is quoted: infertile (1 paper).